TIMP1 (TIMP metallopeptidase inhibitor 1)
Diseases named in the same sentence as TIMP1 in open-access papers (continued):
Sharing a sentence is not in itself a finding about the gene and the disease.
triple-negative breast carcinoma (5 papers, 2016 to 2025). An invasive breast carcinoma which is negative for expression of estrogen receptor (ER), progesterone receptor (PR), and human epidermal growth factor receptor 2 (HER2). "We recently described the expression of TIMP1 in CTCs from patients with triple negative breast cancer associated with a poor prognosis and we also demonstrated its role for promoting the tumor growth in vitro and in vivo." (PMID 32423054, 2020). "In this study, we investigated the functional and molecular mechanisms by which TIMP-1 influences triple-negative breast cancer (TNBC)." (PMID 27130446, 2016). "Together, these data suggest that blocking TIMP-1 activity might be an effective approach for treating triple-negative breast cancer." (PMID 27130446, 2016). "Eugenol-treated cells showed significantly decreased MMP2 and MMP9 expression and an insignificant increase in TIMP1 expression in HER2 positive and triple negative breast cancer cells." (PMID 30518369, 2018). "Our findings suggest that TIMP-1 is a biomarker indicative of a poor prognosis in TNBC patients and that targeting TIMP-1 may provide an attractive therapeutic intervention specifically for triple-negative breast cancer patients." (PMID 27130446, 2016).
acute respiratory failure (4 papers, 2021 to 2023). Life-threatening respiratory failure that develops rapidly. "In clinical cohorts, TIMP-1 systemic level was significantly higher in ARDS subjects than in other sub-groups of ventilated patients with respiratory failure, and it was independently associated with 90-day mortality and worse hypoxemia." (PMID 36482481, 2022). "Recently, a novel investigation of TIMP-1 found elevated systemic TIMP-1 was associated with worse hypoxemia and increased 90-day mortality in a large cohort of mechanically ventilated ARDS patients with respiratory failure." (PMID 36482481, 2022). "Similar to our findings, other studies have showed that respiratory failure, as defined by a P/F ratio, was negatively correlated with increased plasma MMP-9 and TIMP-1." (PMID 37509076, 2023).
Airway obstruction (4 papers, 2012 to 2023). Obstruction of conducting airways of the lung. "Furthermore, a low ratio of MMP-9/TIMP-1 (tissue inhibitor of metalloproteinase 1) has been associated with airway obstruction, suggesting that an excess of TIMP-1 compared to MMP-9 could be responsible for airway remodeling." (PMID 22906131, 2012). "We also observed a significant negative correlation between TIMP-1 and TIMP-2 with FEV1% predicted only in the AE-COPD group, indicating that both TIMPs are associated with airway obstruction in COPD." (PMID 26126526, 2015). "Similarly, Beeh and colleagues demonstrated that both MMP-9 and TIMP-1 were elevated in COPD patient sputum, and MMP-9 negatively correlated with airway obstruction but not with either diffusion capacity or vital capacity." (PMID 36935521, 2023).
alcohol (4 papers, 2015 to 2024). "Furthermore, TIMP-1 was downregulated while MMP9 levels were elevated in subjects with alcohol intoxication in our study." (PMID 39518903, 2024).
amyotrophic lateral sclerosis (4 papers, 2012 to 2022). Amyotrophic lateral sclerosis (ALS) is a neurodegenerative disease characterized by progressive muscular paralysis reflecting degeneration of motor neurons in the primary motor cortex, corticospinal tracts, brainstem and spinal cord. "It has been reported that the TIMP-1 levels were elevated in serum and cerebrospinal fluid samples of amyotrophic lateral sclerosis, which causes a progressive degeneration of motor neurons." (PMID 36362162, 2022). "TIMP1 and TIMP 2 emerge as useful diagnostic markers in neurodegenerative diseases: TIMP 1 level elevates in the CSF in Alzheimer’s and Parkinson’s diseases as well as in amyotrophic lateral sclerosis (ALS), while TIMP-2 levels increase in Alzheimer’s and Huntington’s diseases." (PMID 36232390, 2022).
autoimmune disease (4 papers, 2013 to 2025). A disorder resulting from loss of function or tissue destruction of an organ or multiple organs, arising from humoral or cellular immune responses of the individual to their own tissue constituents. "The correlation between TIMP1 concentration and disease severity in patients with a variety of autoimmune diseases has lead most researchers to conclude that the presence of TIMP1 is acting to limit inflammation." (PMID 23555662, 2013). "We were next interested in ascertaining whether TIMP1 was important for the ability of Th1 and Th17 polarized cells to mediate autoimmune disease." (PMID 23555662, 2013).
bacterial meningitis (4 papers, 2012 to 2025). Inflammation of the membranes surrounding the brain and spinal cord due to a bacterial infection. "Elevated TIMP1 levels have also been reported in serum and cerebrospinal fluid during severe Plasmodium falciparum malaria and during viral or bacterial meningitis." (PMID 40265926, 2025). "Studies have shown that increased concentrations of metalloproteinase inhibitor 1 (TIMP1) in cerebrospinal fluid were part of the host response to bacterial meningitis." (PMID 34972134, 2021). "In previous studies, a positive correlation was shown between CSF TIMP-1 and MMP-9 in patients with bacterial meningitis; however, disease activity was higher in these patients and proteins were measured in CSF, which may explain the contradictory results." (PMID 36766708, 2023).
cerebral aneurysms (4 papers, 2015 to 2023). "Increased mRNA expression of both MMP-9 and TIMP-1 in cerebral aneurysms was found in animal models." (PMID 25932641, 2015). "In a rat cerebral aneurysm model, researchers found that TIMP-1 and TIMP-2 predominantly exist in VSMCs and exhibit high expression levels within cerebral aneurysms." (PMID 37925414, 2023). "Additionally, TIMP-1 and TIMP-2 were shown to have a protective role for the progression of cerebral aneurysms, which suggests that TIMPs may help prevent the degradation of ECM and rupture of cerebral aneurysms." (PMID 30518145, 2018).
cholestasis (4 papers, 2003 to 2021). Impairment of the bile flow caused by obstruction within the liver, or outside the liver in the bile duct system. "Changes in elimination do not explain the differences in MMP and TIMP-1 serum levels, since during chemotherapy both serum creatinine and parameters of cholestasis remained unaltered." (PMID 12698191, 2003). "Similarly, the levels of TC, TBA, γ-GT, TBIL, the expression of TNF-α, TIMP-1, and the BAX/BCL-2 ratio were significantly increased in cholestasis-induced rats compared with the control rats, and these changes were effectively alleviated following treatment with ZYP." (PMID 34539394, 2021).
cholesteatoma (4 papers, 2012 to 2024). A pathologic process characterized by the proliferation of keratinizing squamous epithelium resulting in the accumulation of keratin and cells in the middle ear and/or mastoid. "Also, TIMP-1, which is an MMP-9 specific inhibitor, was found to be upregulated in cholesteatoma, and it indicates that there is a dynamic balance between these two remodeling factors in cholesteatoma." (PMID 35655767, 2022).
chondrosarcoma (4 papers, 2005 to 2023). A malignant cartilaginous matrix-producing mesenchymal neoplasm arising from the bone and soft tissue. "Interestingly, some studies indicate the prognostic potential of the MMP-1/TIMP-1 ratio—patients with recurrent chondrosarcoma have shown higher values of the MMP-1/TIMP-1 ratio than patients without recurrence." (PMID 38138968, 2023). "However, this mode of binding appears to be insufficient to support bridging to LRP-1 in a complex biological environment, as we found that neither TIMP-1 nor TIMP-2 could increase the rate of MMP-1 endocytosis by HTB94 chondrosarcoma cells." (PMID 32694578, 2020).
diabetic cardiomyopathy (4 papers, 2020 to 2024). Diabetic cardiomyopathy is a disorder of the heart muscle in people with diabetes. "A study has reported that exercise improves cardiac function by regulating the concentrations of MMP‐9 and TIMP1 in diabetic cardiomyopathy mice." (PMID 39364701, 2024). "Another research also has demonstrated that exercise training can regulate the concentration of TIMP‐1 in diabetic cardiomyopathy mice, thereby improving cardiac function." (PMID 38956886, 2024).
diffuse large B-cell lymphoma (4 papers, 2015 to 2023). "Finally, certain lymphoproliferative diseases are also associated with expression of COL6A1, COL18A1, MMP3 and TIMP1, and a subset of patients with diffuse large B cell lymphoma and adverse prognosis show decreased expression of POSTN, SPARC, COL1A1, COL3A1,CSTK, MMP9 and LAMB3." (PMID 33379263, 2020). "Similarly, in case of patients with diffuse large B-cell lymphoma treated with modern chemotherapy with or without CD20 antibody, MMP-9 and TIMP-1 seem to have lost their prognostic value." (PMID 25190551, 2015).
disc degeneration (4 papers, 2014 to 2025). "Chondrocytes 2 expressing MGP, MT1G, and GPX3 may play a role in reversing calcification and degeneration, and chondrocytes 4 expressing PTGES, TREM1, and TIMP1 may play a role in disc degeneration pain and inflammation." (PMID 35874809, 2022). "Third, we studied the role of EA played in the ECM regulatory factors, including MMP-13, TIMP-1, and BMP-2, in disc degeneration." (PMID 24987434, 2014). "Although these catabolic factors were counteracted by even higher and increasing expression levels of their natural endogeneous inhibitors such as TIMP-1, TIMP-2, TIMP-3 and TIMP-4, we recoded declining levels of aggrecan and collagen II with increased severity of disc degeneration." (PMID 39286594, 2024). "Moreover, despite the concurrent increase of TIMP1, a major MMP inhibitor, alongside MMPs during disc degeneration, TIMP3 exhibits a distinct behaviour, not following the trajectory of cell immunopositivity for ADAMTS during degeneration." (PMID 39890859, 2025).
gastric tumor (4 papers, 2020 to 2026). "The expression levels of CXCR4 and NFE2L2 as well as four differentially expressed NRGs (SPP1, CXCL1, MMP9, and TIMP1) were validated in gastric tumor cells and clinical samples." (PMID 38221932, 2024). "In conclusion, coexpression of MMP-7 and its inhibitor TIMP-1 in gastric tumour tissues is a potential prognostic marker for GC." (PMID 33005257, 2020). "Gastric tumour tissues were stained immunohistochemically to evaluate expression of MMP-7 and TIMP-1." (PMID 33005257, 2020).
gastritis (4 papers, 2010 to 2023). Inflammation of the stomach. "Furthermore, adults with H. pylori-associated gastritis had increased levels of MMP-9 and decreased levels of MMP-2 and TIMP-1 in serum in comparison to healthy volunteers." (PMID 37958643, 2023). "However, the frequencies of circulating TIMP-1 and -2 expressing leukocytes were reduced in this gastritis group of children." (PMID 37958643, 2023). "In contrary to studies among children, adults with H. pylori–related gastritis have shown increased levels of MMP-8 and -9, an unchanged level of MMP-7, and decreased levels of MMP-2 and TIMP-1." (PMID 37958643, 2023). "In adults with H. pylori–related gastritis, increased levels of MMP-8 and -9, an unchanged level of MMP-7 and decreased levels of MMP-2 and TIMP-1 in comparison to healthy volunteers were detected in serum by using ELISA." (PMID 35163805, 2022). "Incubated for 24 h in cell culture medium, gastric mucosal biopsies from H. pylori–positive patients with chronic superficial gastritis produced higher levels of MMP-9 and TIMP-1, in comparison with biopsies from H. pylori–negative individuals." (PMID 35163805, 2022). "Furthermore, gastric mucosa biopsies from H. pylori-positive patients with gastritis after incubation with culture medium also produced higher levels of MMP-9 and TIMP-1 than biopsies from H. pylori-negative patients." (PMID 37958643, 2023).
Granuloma (4 papers, 2015 to 2022). A compact, organized collection of mature mononuclear phagocytes, which may be but is not necessarily accompanied by accessory features such as necrosis. "In contrast, in CD patients TIMP-1 expression in the glandular epithelium was inversely related to the patients' age (p = 0.049, R = −0.669) while its response in the inflammatory infiltrate was associated with the presence of granulomas (p = 0.016, R = 0.848)." (PMID 27034654, 2016).
head and neck squamous cell carcinoma (4 papers, 2004 to 2023). A squamous cell carcinoma that arises from any of the following anatomic sites: lip and oral cavity, nasal cavity, paranasal sinuses, pharynx, larynx, and salivary glands. "Additionally, patients with high TIMP1 expression had low survival rates in head and neck squamous cell carcinoma (HNSCC)." (PMID 36800936, 2023). "Experimental validation using qPCR and immunofluorescence revealed CAF-specific higher expression of TIMP-1 and COL1A2 as compared to other markers in 5 novel CAF cells, derived from patients of diverse gender, habits and different locations of head and neck squamous cell carcinoma (HNSC)." (PMID 37626157, 2023).
Hepatitis (4 papers, 2009 to 2023). Inflammation of the liver. "Serum TIMP-1 was reduced in both viral and alcoholic cirrhosis and hepatitis." (PMID 36551935, 2022). "In this study, we showed that MSI-1436 reduced ex-vivo liver inflammation and fibrosis by activating antifibrotic factors including TIMP-1 and thus might be considered as a future molecule for the treatment of liver-related inflammation and fibrosis in equine metabolic syndrome affected horses." (PMID 37808009, 2023).
joint disease (4 papers, 2005 to 2023). "Joint effusion is associated with growth factors (BDNF, FGF, IGFBP), stromelysin, and MMP-inhibitor, while joint movement pain and degradation are associated with TIMP-1, ADAMT-4, and ADAMT-5 biomarkers." (PMID 37241010, 2023). "The levels of IL-1β, IL-8 and MMP-8, as well as the MMP-8/TIMP-1 ratio were higher in subjects with muscle and joint diseases." (PMID 23637817, 2013). "Muscle and joint diseases were associated with increased IL-1β, MMP-8 and the ratio MMP-8/TIMP-1." (PMID 23637817, 2013).
kidney failure (4 papers, 2016 to 2024). An acute or chronic condition that is characterized by the inability of the kidneys to adequately filter the blood. "In our study, as all patients presented with kidney failure, the magnitude of the association of TIMP-1 with aging was not very strong, and the variable showed no independent association with age in the multiple regression model." (PMID 38542300, 2024). "We studied 10 LTA recipients with or without kidney failure (KF) and measured serum levels of OPN and TIMP-1 (previously identified predictors of KR), 92 proinflammatory proteins (Olink), and urinary cell populations." (PMID 39440014, 2024).
liposarcoma (4 papers, 2019 to 2025). A usually painless malignant tumor that arises from adipose tissue. "TIMP4 expression in turn is relatively high in well-differentiated liposarcoma and low in the more aggressive undifferentiated liposarcoma, whereas TIMP1 shows an opposite expression pattern in these sarcomas." (PMID 31466240, 2019). "In patients with dedifferentiated liposarcoma (DDLS), the conversion of Tissue Inhibitors Of Metalloproteinase 4 (TIMP-4) to TIMP-1 is associated with poor prognosis.TIMP-1 knockout, TIMP-4 overexpressing, or VP-mediated YAP/TAZ blockade can inhibit the proliferation and migration of DDLS cells." (PMID 33178014, 2020). "Recent genetic studies have identified distinct molecular profiles in liposarcomas: well‐differentiated liposarcomas exhibit high levels of TIMP‐4 and low YAP/TAZ expression, whereas dedifferentiated liposarcomas show elevated TIMP‐1 and activated YAP/TAZ levels." (PMID 39872705, 2025).
lymphedema (4 papers, 2012 to 2024). Excess fluid collection in tissues, causing swelling. "TIMP1 copy number associations were similar but also included systolic blood pressure, lymphedema and webbed neck." (PMID 30281655, 2018).
metastatic carcinoma (4 papers, 2016 to 2023). A carcinoma which has spread from the original site of growth to another anatomic site. "The study yielded glycoforms of tissue inhibitor of metalloproteinase 1 (TIMP1) and protein tyrosine phosphatasek (PTPk), which play important roles in invasive and metastatic cancer cells and are known targets of N-acetyl glucosaminyl transferase (GnT-V)." (PMID 28265552, 2017).
non-alcoholic fatty liver disease (4 papers, 2017 to 2025). "In patients with severe obesity-associated non-alcoholic fatty liver disease (NAFLD), LEAP-2 has been found to slightly induce the upregulation of factors involved in fibrogenesis such as α-SMA, COL1α1, and TIMP1 via the PI3K/Akt/mTOR signaling pathway." (PMID 39860298, 2025). "Nonalcoholic fatty liver disease (NAFLD), often present in the obese patients, is associated with increased serum concentrations of MMP-2, MMP-9, TIMP-1, 2, TGF-beta concentrations." (PMID 38541059, 2024).
nonalcoholic steatohepatitis (4 papers, 2021 to 2025). "It was previously reported that Timp1 was increased in the liver from adipocyte-specific nuclear form of SREBP-1c (nSREBP-1c) transgenic mice, showing human nonalcoholic steatohepatitis (NASH)." (PMID 34539442, 2021). "In a mouse model of non-alcoholic steatohepatitis (NASH), SR9009 was reported to reduce glucose levels, improve glucose tolerance, and inhibit the expression of fibrotic markers, such as collagen α1(III) (COLl3A1), α-SMA, STAT1, MMP13, TIMP1, and TGF-β." (PMID 40255337, 2025). "In addition, pirfenidone prevented myocardial steatosis and fibrosis in a mouse model of nonalcoholic steatohepatitis (NASH) by overexpressing PPARα, PPARγ, ACOX1, and CPT1A protein levels and decreasing Timp1, Col I, Col III mRNA levels." (PMID 33809061, 2021).
peripheral arterial disease (4 papers, 2020 to 2025). A disorder of the arteries supplying the upper and lower extremity and the visceral organs. "For example, levels of MMP- 2, MMP- 9, and TIMP1 increase in circulation in patients with peripheral arterial disease (PAD) [1335, 1336]." (PMID 40407975, 2025). "In clinical studies, abnormal circulating levels of MMP-1, -2, -8, -9, and TIMP-1 were found in patients with Peripheral Arterial Disease; their increase was attributed to the presence of ischemic tissue." (PMID 31963569, 2020).
Pleural effusion (4 papers, 2019 to 2025). The presence of an excessive amount of fluid in the pleural cavity. "Pleural effusion Galectin-1, NRG1-β1, Osteopontin, Mesothelin, shed SDC-1, VEGF and TIMP-1 levels are more reliable diagnostic biomarkers than HGF and MMP in pleural effusion." (PMID 32731396, 2020). "Cytokine array analysis and EIA confirmed that fucoidan lowered the expression levels of inflammatory cytokines such as TIMP-1, CXCL1, MCP-1, MIP-2, and IL-1Ra in pleural effusion of irradiated mice." (PMID 40438605, 2025). "In order to determine the prognostic value of pleural effusion derived Angiopoietin-1, HGF, MMP-7, Osteopontin, TIMP-1, Galectin, Mesothelin, NRG1-b1, SDC-1 and VEGF, we divided patients in two groups depending on the established cut-off value for all analytes." (PMID 32731396, 2020).
pressure ulcers (4 papers, 2008 to 2022). "Pressure ulcers have increased levels of MMP9 and decreased levels of tissue inhibitor metalloproteinase-1 (TIMP-1), and wounds with higher MMP9 and lower TIMP-1 activity heal slower than those with opposite relative levels." (PMID 33374656, 2020). "In addition, GM-CSF, IFN-γ, MMP-3, and TIMP-1 were not reported previously in the wound healing process, and those genes may have a role in development of the pressure ulcers." (PMID 26177082, 2015).